GNL1 (G protein nucleolar 1)
Description:
Possible regulatory or functional link with the histocompatibility cluster.
Synonyms: HSR1
Tractability: PROTAC: ubiquitination databases record sites on it; its protein half-life has been measured.
Gene: Protein-coding gene on chromosome 6 (30,541,381 to 30,556,603, reverse strand). Ensembl gene ENSG00000204590.
Subcellular location (Human Protein Atlas): Vesicles
Gene Ontology:
Molecular function: GTP binding; GTPase activity; structural molecule activity
Biological process: DNA damage response; signal transduction; T cell mediated immunity
Cellular component: nucleus; extracellular region
Genetic constraint (gnomAD): Loss-of-function variants: 15 observed, 65.01 expected, observed/expected ratio (o/e) 0.23, 90% interval 0.15 to 0.35. The upper end of that interval is the gene's LOEUF score, 0.35, which puts it in group 1 of 6, group 1 being the genes least tolerant of losing a copy. Missense variants: 495 observed, 670.29 expected, observed/expected ratio (o/e) 0.74, 90% interval 0.69 to 0.8. Synonymous variants: 245 observed, 265.16 expected, observed/expected ratio (o/e) 0.92, 90% interval 0.83 to 1.03.
Homologues: Orthologues: macaque GNL1 (99% identical), dog GNL1 (98% identical), chimpanzee GNL1 (96% identical), mouse Gnl1 (95% identical), pig GNL1 (95% identical), rat Gnl1 (92% identical), guinea pig GNL1 (91% identical), tropical clawed frog gnl1 (65% identical), rabbit GNL1 (57% identical), zebrafish gnl1 (57% identical), Drosophila melanogaster Ns4 (42% identical). Paralogues in human: LSG1 (23% identical), GNL2 (18% identical), GNL3 (18% identical), GNL3L (16% identical), NOA1 (14% identical), MTG1 (10% identical).
Diseases named in the same sentence as GNL1 in open-access papers:
GNL1 is named in the same sentence as 16 diseases in open-access papers, as found by Europe PMC text mining. Sharing a sentence is not in itself a finding about the gene and the disease. The quoted sentences say what the papers report.
gastric cancer (2 papers, 2015 to 2018). A primary or metastatic malignant neoplasm involving the stomach. "Expression of GNL1 and RPS20 induced the colony forming ability of colon and gastric cancer cell lines provided evidence for the role played by GNL1 and RPS20 during cancer progression." (PMID 30061673, 2018). "Based on GNL1 expression pattern, colorectal and gastric cancer cell line systems were selected to further understand the functional relevance of GNL1 upregulation during tumorigenesis." (PMID 30061673, 2018). "Kaplan-Meier analysis showed that high mRNA expression of GNL1 and RPS20 was strongly associated with decreased overall survival of gastric cancer patients." (PMID 30061673, 2018). "Aberrant methylation at the genes B3GATL4 (6p21.3), TNXB (6p21.3), TRIM31 (6p21.3), LY6G5C (6p21.33), KIAA1949/PPP1R18 (6p21.3), and GNL1 (6p21.3) identified in NPC was also hypermethylated in EBV-positive gastric cancers compared to EBV-negative gastric cancers (FDR < 1.6 × 10−90)." (PMID 25924914, 2015). "Finally, the inverse correlation of GNL1 and RPS20 expression in primary colon and gastric cancers with patient survival strengthen their critical importance during tumorigenesis." (PMID 30061673, 2018). "In addition, analysis of gene expression databases suggested that the expression of GNL1 and RPS20 in primary colon and gastric cancers inversely correlated with patient survival further strengthen their critical role in tumorigenesis." (PMID 30061673, 2018).
Parkinson disease (2 papers, 2021 to 2022). A progressive degenerative disorder of the central nervous system characterized by loss of dopamine producing neurons in the substantia nigra and the presence of Lewy bodies in the substantia nigra and locus coeruleus. "The RNA G-quadruplex in the 5′ UTR region of VPS35 and PRKN binds with guanine nucleotide binding protein like-1 (GNL-1), causing dysregulation of the genes associated with Parkinson’s disease." (PMID 36360167, 2022).
astrocytoma (1 paper, 2020). "Furthermore, we also measured the protein levels of four selected RBPs (GNL1, SPATS2L, RDM1, and FBXO17) in three glioma cell lines, one astrocytoma cell line (SW1088) and two glioblastoma cell lines (U251 and LN229)." (PMID 33634092, 2020).
breast carcinoma (1 paper, 2017). "Several interactors in this group were also identified as substrates, including the RNA helicase DDX10, the guanine nucleotide binding protein GNL1 and RRP1B, a ribosomal RNA processing protein which has been linked as a susceptibility marker in breast cancer." (PMID 29214152, 2017).
epilepsy (1 paper, 2021). A brain disorder characterized by episodes of abnormally increased neuronal discharge resulting in transient episodes of sensory or motor neurological dysfunction, or psychic dysfunction. "Patient P_000512 with short segment HSCR, epilepsy and intellectual disability, has a large de novo deletion (6p22.1—p21.33) which affects the ENS genes GABBR1, GNL1 and TUBB." (PMID 34358225, 2021).
infertile (1 paper, 2015). "A highly significant difference of normozoospermic fertile and infertile subjects was confirmed also when the density of mannose glycoepitopes was estimated as the ratio of total lectin reactivity to protein content in bands GNL-1–4 (p < 0.001)." (PMID 26147424, 2015).
type 1 diabetes (1 paper, 2011). "The detailed examination of the relationship between gene GNL1 and gene PPP1R10 may provide some new insights in studying the causes of type 1 diabetes." (PMID 21569557, 2011).
cancer (3 papers, 2018 to 2023). A tumor composed of atypical neoplastic, often pleomorphic cells that invade other tissues. "GNL1 (Guanine nucleotide binding protein like 1) promotes cancer cell proliferation by modulating G1/S and G2/M phase transition, while TLK2 (Tousled‐like kinases 2) is important in chromatin assembly and maintenance of replication fork integrity." (PMID 36775869, 2023). "Results from this analysis suggested that GNL1 expression was upregulated in majority of the cancers." (PMID 30061673, 2018). "Towards this, we first determined the cell survival/proliferation by MTT and BrdU incorporation assays upon ectopic expression of GNL1 in colorectal (HCT116p53+/+) and gastric (AGS) cancer cell lines." (PMID 30061673, 2018).
tumour (1 paper, 2012). "Repositioning of the centromere was also detected, and reordering of many of the genes remaining on chromosome 4 in the tumour (e.g.GNL1 and RUNX2)." (PMID 22359511, 2012).
GNL1 also shares sentences with these, for which no sentence is quoted: colorectal cancer (2 papers); breast tumor (1); cervical cancer (1); channelopathy (1); glioblastoma (1); glioma (1); Intellectual disability (1).